CCR2 (C-C motif chemokine receptor 2)
Diseases named in the same sentence as CCR2 in open-access papers (continued):
Sharing a sentence is not in itself a finding about the gene and the disease.
Hypercholesterolemia (6 papers, 2012 to 2021). An increased concentration of cholesterol in the blood. "The finding that the expression of CCR2 is associated with participants’ LDL-C levels is consistent with previous findings of patients with hypercholesterolemia, including familial hypercholesterolemia." (PMID 33717107, 2021). "A study observed that patients with hypercholesterolemia showed increased expression of CCR2 on classical monocytes, but treating them with PCSK9 inhibitors significantly lowered the expression of the same receptor." (PMID 34884827, 2021). "The important role of CCR2 in atherogenesis has been demonstrated in studies using gene knockout animal models; there was a marked decrease in atherosclerotic lesion formation in apo-E-null mice that lacked CCR2 and increased CCR2 expression is evident in patients with hypercholesterolemia." (PMID 22606372, 2012).
idiopathic pulmonary fibrosis (6 papers, 2021 to 2025). Idiopathic pulmonary fibrosis (IPF) is a nonneoplastic pulmonary disease that is characterized by the formation of scar tissue within the lungs in the absence of any known cause. "In addition, 64Cu-DOTA-ECL1i uptake decreased in a mouse model of idiopathic pulmonary fibrosis (IPF) after treatment with interleukin-1β blockade or antifibrotic pirfenidone suggesting that CCR2-directed PET can be a useful tool for therapeutic monitoring." (PMID 33669804, 2021).
intracerebral hemorrhage (6 papers, 2014 to 2023). A cerebrovascular disorder characterized by bleeding into one or both cerebral hemispheres including the basal ganglia and the cerebral cortex. "CCR2 knockout mice and chimeric mice with WT somatic cell and CCR2 knockout bone marrow-derived cells showed reduced number of Ly6Chi monocytes and mitigated disease outcome with less inflammation after intracerebral hemorrhage." (PMID 32596397, 2020). "The Ly6Chi CCR2+ monocytes have been shown to contribute to acute injury after intracerebral hemorrhage." (PMID 25469644, 2014). "Also, CCR2 KO mice showed acute and transient behavioral improvement after intracerebral hemorrhage (one and three days), but this was not sustained at seven days." (PMID 30332405, 2018).
leukemia (6 papers, 2016 to 2025). A malignant (clonal) hematologic disorder, involving hematopoietic stem cells and characterized by the presence of primitive or atypical myeloid or lymphoid cells in the bone marrow and the blood. "Subsequent investigations demonstrated that CCR2-/- leukemia mice exhibited a significant reduction in peripheral blood leukemia cells, although no discernible difference was detected in the bone marrow." (PMID 38779660, 2024). "Further comprehensive studies revealed that LAMs facilitate the extramedullary distribution of leukemia cells through modulation of the CCL8/CCL9-CCR1/CCR2 axis." (PMID 38779660, 2024). "The histograms show a large population of positive CCR2 leukemia blasts (surrounded in black), 56% (BM) and 53% (PB)." (PMID 28045930, 2017). "Both CXCR4/SDF-1 and VLA-4/VCAM1 axes are involved in leukemia protection but little is known about the role of CCL2/CCR2 in AML biology and protection against chemotherapy." (PMID 28045930, 2017). "Additionally, CCR2-/- leukemia mice displayed less hepatosplenomegaly and fewer leukemia cells compared to WT mice." (PMID 38779660, 2024). "Finally, our results suggest that CCL2/CCR2 axis may have a role in a subset of AML patients, especially in monocytoid AML, which represent the leukemias with higher CCR2 expression." (PMID 28045930, 2017). "This is the first report on the important role of ARC in the regulation of the CCR2/CCL2 and CCR5/CCL4 axes in leukemia and stromal cells." (PMID 26956049, 2016). "We identify that, in addition to the well-known CXCR4/CXCL12 axis, CCR2/CCL2 and CCR5/CCL4 also drive leukemia/stromal interactions." (PMID 26956049, 2016). "Collectively, these results suggest that like CXCR4/CXCL12, the CCR2/CCL2 and CCR5/CCL4 receptor/chemokine axes contribute to leukemia-MSC interactions, and that the chemokines expressed by MSCs are regulated, at least in part, by ARC in AML cells." (PMID 26956049, 2016). "The expression of liver-specific chemokine receptors, such as CCR1, CCR2, and CCR5, on leukemic cells facilitates their homing to the liver, where they acquire leukemia stem cell (LSC)-like properties, including enhanced self-renewal and proliferative capacity." (PMID 40842579, 2025).
Listeria infection (6 papers, 2012 to 2024). "Limited recruitment of monocytes to the site of infection likely contributes to the enhanced susceptibility of CCR2−/− mice to Listeria infection." (PMID 23094119, 2012). "Interestingly, genetic deletion of CD38 resulted in increased accumulation of inflammatory monocytes in the liver but not in the spleen and was associated with higher susceptibility to listeria infection, as observed during genetic deletion of Ccr2." (PMID 36010615, 2022). "Lastly, adoptive transfer experiments in the context of Listeria infection showed that Ccr2–/– monocytes are still able to traffic to the site of infection in the spleen and liver." (PMID 39541153, 2024). "To address the question whether the gain of function upon PPARγ ablation in macrophages is already sufficient to improve control of Listeria infection in the absence of inflammatory monocytes, we adoptively transferred PPARγ-deficient macrophages into CCR2−/− mice." (PMID 22629382, 2012).
lupus (6 papers, 2010 to 2023). "In addition, CCR2 deficiency affects not only monocytes or macrophages and T‐cell infiltration in lupus kidney but also systemic T‐cell response in lupus mice." (PMID 35875970, 2022). "In lupus-prone mice, CCR2 and CCL2 are increased in the kidney during the development of LN, suggesting the recruitment of CCR2+ leukocytes into the inflamed kidney by CCL2." (PMID 27403037, 2016). "Taken together, low ROS production due to NCF1 deficiency enhances AKT/mTOR-dependent pDC generation and promotes pDC migration via CCR2, which may explain the accumulation of pDCs during lupus." (PMID 36853827, 2023). "Furthermore, we observed CCR2 upregulation on NCF1-deficient pDCs, which may favor their migration and accumulation during lupus." (PMID 36853827, 2023). "CCL2 is an emerging novel target in systemic lupus erythematosus (SLE) and lupus nephritis, in which the CCL2/CCR2 axis mediates the infiltration of macrophages and T cells into the nephron in nephritis." (PMID 35702353, 2022). "By blocking the interaction between CCR2 and CCL2 in MRL/lpr lupus-prone mice, studies have shown that CCL2/CCR2 network contributes to LN development through both systemic and local mechanisms." (PMID 27403037, 2016).
medulloblastoma (6 papers, 2011 to 2024). A malignant, invasive embryonal neoplasm arising from the cerebellum. "M0 and M1 cells expressed Igf1, which has been shown to promote medulloblastoma progression, while M2 expressed Ccr2, which is associated with tumor-inhibiting macrophages." (PMID 34021242, 2021). "We here demonstrate that medulloblastoma cells of both murine and human origins express CCR2 and are susceptible to GMME1-mediated apoptosis in vitro." (PMID 21943176, 2011). "Progenitor-triggered medulloblastomas also contained more diverse stromal populations, with more Ccr2+ macrophages and fewer Igf1+ microglia, indicating that developmental events affected the subsequent tumor microenvironment." (PMID 34021242, 2021). "To define the cellular identity of TAMs in medulloblastoma, we utilised orthotopic intra-cranial allografts of SmoA1 medulloblastoma into Ccr2+/RFPCx3cr1+/GFP double knock-in mice." (PMID 31160587, 2019). "A Kaplan–Meier survival curve illustrated a significant decrease in median survival for Ccr2RFP/RFP (53 days) mice bearing medulloblastoma compared to Ccr2+/+ mice (83 days)." (PMID 31160587, 2019). "This was repeated in our model of medulloblastoma which demonstrated that CCR2+HSCs are responsible for the capacity of HSC transfer to enhance the efficacy of adoptive cellular therapy." (PMID 30333482, 2018). "In mice bearing Ptc medulloblastoma, combinatorial CCR2+HSCs + PD-1 also provided a significant survival benefit over both PD-1 only (p = 0.0001) and bulk HSC + PD-1 (p = 0.0005)." (PMID 30333482, 2018).
mesothelioma (6 papers, 2016 to 2025). A usually malignant and aggressive neoplasm of the mesothelium which is often associated with exposure to asbestos. "Consequently, therapies that prove effective against other cancers in which the CCL2/CCR2 axis and myeloid-derived cells are associated with disease progression may also prove effective with mesothelioma patients." (PMID 31823764, 2019). "This is consistent with the premise that the CCL2/CCR2 axis and myeloid-derived cells play an important role in mesothelioma and disease progression." (PMID 31823764, 2019). "Since mesotheliomas are heavily infiltrated by macrophages and likely to be infiltrated by MDSCs, our finding that CCL2 is elevated in the serum of patients with advanced mesothelioma is consistent with a disease in which the CCL2/CCR2 axis and myeloid-derived cells play an important part." (PMID 31823764, 2019). "Given that the chemokine receptors CCR2 and CCR5 have been shown to be important in migration towards mesothelioma tumors, we next observed the expression of these receptors on CD26high T cells." (PMID 29213079, 2017).
metabolic syndrome (6 papers, 2012 to 2024). A cluster of metabolic risk factors for CARDIOVASCULAR DISEASES and TYPE 2 DIABETES MELLITUS. "While extensively studied in other inflammatory conditions, CCR2′s relevance to metabolic syndrome is debated, necessitating careful interpretation of our results." (PMID 39199602, 2024). "CX3CR1 up-regulation in platelet-Mon1 monocyte aggregates in metabolic syndrome patients led to increased CX3CR1/CCR2-dependent platelet-Mon1 monocyte adhesion to dysfunctional arterial endothelium." (PMID 31109070, 2019). "Moreover, blueberry supplementation has been shown to decrease monocyte expression of monocyte-to-macrophage differentiation-associated (MMD) and C-C motif chemokine receptor 2 (CCR2), reducing inflammation in metabolic syndrome patients." (PMID 38558823, 2024). "Additionally, CX3CL1/CX3CR1 or CCL2/CCR2 axes are potential candidates for therapeutic intervention in cardiovascular disorders in metabolic syndrome patients, as their blockade impairs the augmented arterial platelet-Mon1 monocyte aggregate adhesiveness, which is a key event in atherogenesis." (PMID 31109070, 2019). "We characterized immune cell behavior in metabolic syndrome, its consequences, and the potential involvement of the CX3CL1/CX3CR1 and CCL2/CCR2 chemokine axes." (PMID 31109070, 2019).
prostate tumor (6 papers, 2019 to 2026). "We found that CCR2 tissue expression in prostate tumours was associated with PSA blood level." (PMID 39199567, 2024). "High levels of CCR2 exist in prostate tumor cell surface to respond to autocrine and/or paracrine CCL2 in the microenvironment." (PMID 32471499, 2020). "Third, we observed PSMP chemoattracted monocyte/macrophage infiltration in a CCR2-dependent manner and influenced macrophage differentiation to change the microenvironment of prostate tumors by indirectly." (PMID 31555577, 2019). "We hypothesized that PSMP is an important secreted protein that has an impact on prostate tumor formation, metastasis, and microenvironment through its receptor CCR2, expressed on PCa cells and immune cells." (PMID 31555577, 2019). "This corresponds well to our finding that fibroblast-mediated signaling towards Ccr2 contributes to macrophage recruitment and is interrupted upon castration, and suggests that androgen deprivation decreases macrophage abundance in the prostate tumor environment." (PMID 36511483, 2022). "HFD can induce prostate tumor growth through a large suite of chemical signaling pathways, such as the activation of IL6/pSTAT3 or MCP-1/CCR2 signalings, or through the inhibition of tumor suppressor gene PTEN." (PMID 31011360, 2019). "By combining single-cell and spatial transcriptomics, along with flow cytometry and immunohistochemical analyses, we now reveal that prostatic tumors of such mice are hypoxic and progress within a complex immune microenvironment, including neutrophils, TREM2+ macrophages, and CCR2+ myeloid cells." (PMID 41896221, 2026). "The results demonstrate that despite being expressed in prostate tumours, CCR2 and CCL2 have no prognostic value in the disease." (PMID 39199567, 2024).
respiratory infection (6 papers, 2011 to 2025). "To elucidate the mechanisms underlying infection susceptibility in ccr2-/- mice, we assessed the temporal accumulation of myeloid cells in the lung following C. muridarum respiratory infection." (PMID 39903705, 2025). "To clarify the relationship between CCR2 and the clearance of chlamydial infections, we established a respiratory infection model using WT and ccr2-deficient (ccr2-/-) mice." (PMID 39903705, 2025). "The increased susceptibility of ccr2-/- mice to C. muridarum respiratory infection is linked to a profound impairment in the accumulation and functional activity of both innate and adaptive immune cells." (PMID 39903705, 2025). "In this study, we investigated the role of CCR2 in the host response to C. muridarum respiratory infection, revealing its critical involvement in regulating both innate and adaptive immune responses." (PMID 39903705, 2025). "In this study, we employed ccr2-/- mice to investigate the role of CCR2 in a Chlamydia muridarum respiratory infection model." (PMID 39903705, 2025). "Our study emphasizes the multifaceted role of CCR2 in modulating immune responses during C. muridarum respiratory infection." (PMID 39903705, 2025). "Our results demonstrate that CCR2 expression on naïve CD4+ T cells is initially low and significantly upregulated by day 7 p.i. following C. muridarum respiratory infection, although the expression remains at a relatively low level." (PMID 39903705, 2025). "To determine the effects of monocyte depletion on cytokine production during S. aureus respiratory infection, we quantified cytokines and chemokines in the BALF of WT and CCR2-depleted mice, 4 h and 24 h post intranasal infection." (PMID 39418302, 2024). "A number of the genes in this signature have known connections to the immune response and the outcome of respiratory infections, e.g., genes for the chemokines osteopontin (SPP1) and RANTES (CCL5) and the chemokine receptor CCR2." (PMID 22189154, 2011). "Collectively, the results imply that reduced migration of inflammatory monocytes in the absence of CCR2, and any resulting reductions in cells that differentiate from these, has less impact on survival of respiratory infections than on systemic infections." (PMID 33760886, 2021).
toxoplasmosis (6 papers, 2014 to 2024). A parasitic disease contracted by the ingestion or fetal transmission of toxoplasma gondii. "We aimed to confirm whether the adoptive transfer of inflammatory monocytes to CCR2-deficient mice contributes to protection against lethal toxoplasmosis, as previously reported." (PMID 39051675, 2024). "Therefore, mice deficient in the chemokine receptor CCR2, which promotes the recruitment of inflammatory monocytes to sites of inflammation during toxoplasmosis, were immunized with cpsII-OVA parasites." (PMID 24722202, 2014). "The protective role of these monocytes is demonstrated by the fact that both CCR2- and CCL2-deficient mice succumb to lethal toxoplasmosis, and that the adoptive transfer of CCR2-competent Ly6Chi monocytes can rescue this lethality." (PMID 24942685, 2014). "Toxoplasmosis is lethal in CCR2- and CCL2-deficient mice and can be rescued by the adoptive transfer of CCR2-competent Ly6Chi monocytes, suggesting a protective role for Ly6Chi monocytes and their progeny." (PMID 24726741, 2014). "CCR2−/− mice or CCL2−/− mice failed to recruit Gr1+ inflammatory monocytes, which are required for mucosal resistance to T. gondii, or to control systemic toxoplasmosis by intraperitoneal infection." (PMID 24661782, 2014).
uveitis (6 papers, 2007 to 2025). An inflammatory process affecting a part of or the entire uvea. "The genes that showed a significantly increased risk ratio for uveitis in the uveitis only group, and were upregulated in patients, included CCR2, CD180, GAPT, and PTGS2." (PMID 40270958, 2025). "Subgroup analysis also did not reveal any association of chemokine SNPs with any phenotype of IPSU apart from CCR2 64I allele, which was slightly higher in patients with intermediate uveitis (12%) when compared to the controls (7%; p=0.03, pc=0.09)." (PMID 17417600, 2007). "Some of the genes that were identified as important classifiers of the uveitis only group, such as P2RY2 and CCR2, are known to be relevant in the pathogenesis of uveitis." (PMID 40270958, 2025). "Machine learning identified IFN-associated genes as robust predictors, while linear discriminant analysis pinpointed CCR2, CD180, GAPT, and PTGS2 as key risk factors in isolated uveitis and CA1, SIAH2, and PGS in systemic disease-associated uveitis." (PMID 40270958, 2025). "With CCR2 V64I SNP we noticed a nonsignificant trend of increased frequency of 64I allele in patients with intermediate uveitis as compared to controls (p=0.03, pc=0.09)." (PMID 17417600, 2007). "Cells with high expression of CCR2 have previously been demonstrated in the eye fluid of uveitis patients, while the absence of these gene products attenuates eye lesions through decreased cytokine secretion or reduced uveitis antigen-specific T-cell activation." (PMID 40270958, 2025). "For instance, metaDEGs of the uveitis only group comprise genes that are involved in the innate immune response, such as chemokine receptors (CX3CR1, CCR1, and CCR2), and Toll-like receptors (TLR4, TLR7, TLR8, and the TLR4 homologous receptor, CD180)." (PMID 40270958, 2025). "For instance, in the uveitis only group, the genes KLHL21, MYLIP, ZNFX1, PDE4A, TNFRSF21, and N4BP2L2 were downregulated, while METTL72, GAPT, CD180, CCR2, and TLR7 were upregulated when comparing uveitis patients with healthy controls." (PMID 40270958, 2025). "Notably, our previous induced uveitis rodent studies demonstrated SOCS1-KIR mediated decreases in the chemokines CCL2, CCL20 and CXCL9, in addition to the chemokine receptors CCR2, CCR4, CCR6 and CXCR35,25." (PMID 35505065, 2022). "Comparison of classical monocytes between HC and uveitis patients revealed that common monocytic markers, e.g., CCR2, CX3CR1, HLA-DR, HLA-ABC, IL-6, IL-1β, and TNF-α were not affected (data not shown)." (PMID 30105034, 2018). "Single-cell analysis supported that CD1c+ DCs in eye fluid of patients with non-infectious uveitis contain also a population that has a gene profile reminiscent of CX3CR1+ DC3s, with relatively higher levels of CX3CR1, CD36, CCR2, and lower levels of RUNX3." (PMID 37042831, 2023).